BRCA1 (BRCA1 DNA repair associated)
Diseases named in the same sentence as BRCA1 in open-access papers (continued):
Sharing a sentence is not in itself a finding about the gene and the disease.
melanoma (continued). "Interestingly, though the BAP1 protein associates with BRCA1, the data to support melanoma predisposition in carriers of either BRCA1 or BRCA 2 is mixed." (PMID 34638397, 2021). "In conclusion, the constitutive deregulation of BRCA1 pathway genes and the immune response in healthy skin could be a mechanism related to melanoma risk." (PMID 34660619, 2021). "By “pooling” all subtypes together in this way it is possible that any statistical signal that might link BRCA1 or BRCA2 variants to rarer melanoma subtypes could be diluted." (PMID 31610093, 2020). "Moreover, the BRCA2 mutations carriers have greater risk of bile duct, gall bladder, pancreatic, gastro-intestinal tumors, and melanoma, while the BRCA1 mutations carriers of CC." (PMID 33287145, 2020). "Evidence suggesting possible association between BRCA1 mutations and melanoma is weak." (PMID 30286154, 2018). "Furthermore, high expression of DNA repair pathways was associated with metastasis in melanoma patients, and BRCA1 showed a higher expression level in metastatic patients." (PMID 26024915, 2015). "Because cancers other than breast, ovary, pancreas, and prostate, and melanoma could be related to BRCA1/2 mutations, we also estimated risks of mortality with censoring at time of diagnosis of any cancer." (PMID 19277124, 2009). "Additionally, there may be future indications for both men and women who have deleterious BRCA1/2-associated cancers such as breast, prostate, pancreatic, and melanoma, as more study results are reported." (PMID 29670811, 2016). "The data showed that in melanoma cells with stable knockdown of BRCA1, CUL3, RNF4, UBR5, and CHIP, the reduction in CIP2A levels upon PF treatment was not reversed." (PMID 39399646, 2024). "Among them, six E3 ligases were highly expressed in melanoma cells: BRCA1, CUL3, RNF4, UBR5, CHIP, and von Hippel‒Lindau (VHL)." (PMID 39399646, 2024). "The BRCA1 and CHEK1 variants were identified in a rare breast neuroendocrine tumor (GE05) and in a melanoma case (GE14), respectively." (PMID 38750555, 2024). "CtBP1/BARS is also involved in genome instability through its transcriptional regulation of BRCA1 gene, which dampens DNA-damage repair in melanoma." (PMID 38711119, 2024). "We estimated a hazard ratio of 9.90 for a second diagnosis of melanoma after initial diagnosis in BRCA2 mutation carriers and 11.4 for those with a BRCA1 mutation." (PMID 38741145, 2024). "Two patients with monoallelic somatic gene loss also had responses, one with a BRCA1 alteration (HNSCC) and one with a BRCA2 alteration (melanoma)." (PMID 37277454, 2023). "In addition to melanoma susceptibility genes, an increased risk of melanoma has been reported in patients with germline mutations causing cancer syndromes, including hereditary breast and ovarian cancer (BRCA1/BRCA2), Werner syndrome (WRN), and xeroderma pigmentosum (XP)." (PMID 38028607, 2023). "Consistent with this, we found that increasing concentrations of THZ531 decreased BRCA1 and Rad51 protein level, which correlates with a dose-dependent increase in DNA damage in both melanoma cell lines." (PMID 36309522, 2022). "Many HR genes (BRCA1/2 and BAP1) are also related to syndromes that enhance genetic predisposition to cancer, including melanoma." (PMID 35563772, 2022). "In fact, a number of HR-DDR genes, such as BRCA1/2, FANCA and BAP1, are associated with genetic syndromes that increase predisposition to cancers such as melanoma." (PMID 34572747, 2021). "In the Brown modules, the PPI analysis revealed a BRCA1 interaction hub, where BRCA1 and its interacting partners were upregulated in late (stage 4) melanoma versus early (stage 1) melanoma." (PMID 32079144, 2020).
melanoma (continued). "Germline mutations of BRCA1 and BRCA2 are significantly associated with the development of multiple neoplasms, including breast, ovarian, stomach, pancreas, colon, and melanoma." (PMID 32493233, 2020). "A total of 9 patients (3.4%) carried mutations in high-to-moderate melanoma risk genes (CDKN2A, POT1, ACD) and 22 (8.3%) patients in other cancer syndrome genes (NBN, BRCA1/2, CHEK2, ATM, WRN, RB1)." (PMID 33050356, 2020). "Altogether, 7/11 double mutation carriers (excluded from the analysis of clinicopathological data) carried at least one mutation in high-risk melanoma (POT1/CHEK2) or syndromic (ATM/WRN, BRCA1, BRCA2 (2x), CHEK2/RAD51D, NBN) genes." (PMID 33050356, 2020). "Some are well known and strongly associated, like CDKN2A for melanoma, while others are rare (MBD4) or more controversial, like BRCA1/2." (PMID 31382694, 2019). "Studies with JARID1C and BRCA1 were performed in mouse or primary human cells, whereas our data was generated with A375 melanoma cells." (PMID 31114908, 2019). "In contrast to BRCA1, many studies have suggested an association between BRCA2 mutations and melanoma." (PMID 30286154, 2018). "The MM lesion carried a BRAFV600E and a TERT promoter mutation.As the family story was consistent with a genetic predisposition to cancer, we performed mutational analysis of genes involved in familial melanoma and CLL, and of BRCA1 and BRCA2." (PMID 29371889, 2018). "A similar trend was seen in melanoma, within SLX4, POLE, BRCA1, FANCD2, and ERCC6-mutated tumors containing a significantly higher mutational burden than overall melanoma." (PMID 27004405, 2016). "Taken together, this evidence suggests a possible functional link between PTEN and BRCA1 in melanomas." (PMID 24830350, 2014). "Transcripts associated with BRCA1, BRCA2, ATM and CHEK2 showed altered expression in melanoma cell lines after cisplatin treatment." (PMID 23940574, 2013). "In melanoma tumour tissue BRCA1 transcript expression correlated with poor survival and XPB expression correlated with solar elastosis levels." (PMID 23940574, 2013). "The primary melanoma cell line IgR3 was the only melanoma cell line to show increased BRCA1 expression at 24 hours, but it was largely variable with a fold change of 3.17±1.29." (PMID 23940574, 2013). "Moreover, dermatological surveillance has emerged as a formal recommendation in patients with known germline variants, such as BRCA1 and BRCA2 carriers, with an increased risk for melanoma." (PMID 40649916, 2025). "This discrepancy may be explained by differences in perceived disease severity, as most CDKN2A PV carriers had survived melanoma, in contrast to the BRCA1 cohort, where a large percentage of affected relatives in the BRCA1 cohort had died of their disease." (PMID 38822936, 2024). "BRCA1 and BRCA2 pathogenic variants (PVs) are associated with significantly increased lifetime risks of cancers of the breast, ovary, pancreas, prostate, and melanoma." (PMID 39001386, 2024). "During the mean follow-up period of eight years, 3.7% of women with a BRCA1 mutation (133 of 3,623) and 3.8% of women with a BRCA2 mutation (99 of 2,584) reported a diagnosis of skin cancer (including both keratinocyte carcinomas and melanoma)." (PMID 38741145, 2024). "Indeed, in melanoma patients, the increased expression level of CtBP1/BARS correlates with decreased expression and function of BRCA1, and this contribute to genome instability and melanoma initiation." (PMID 38711119, 2024). "It has not been clearly established if skin cancer or melanoma are manifestations of BRCA1 or BRCA2 mutation carrier status." (PMID 38741145, 2024).
melanoma (continued). "In light of this finding, we investigated the possibility that by blocking CtBP1/BARS functions with Comp.11, we could prevent melanoma progression by increasing the BRCA1/BRIP1-controlled DNA-Damage Response Pathway." (PMID 38711119, 2024). "For this purpose, in this work, we genetically tested Sicilian male patients with MBC, PCa, PC and melanoma for germline BRCA1/2 PVs, in order to assess the type and prevalence of these high-risk susceptibility variants in individuals from the southernmost region of Italy." (PMID 38974244, 2024). "In addition, the phosphorylation levels of ATR, ATM, and BRCA1 were significantly increased after 4 Gy X-ray irradiation in B16 and S91 melanoma tumors." (PMID 37507394, 2023). "Additionally, melanoma risk is increased in mixed cancer syndromes caused by mutations in PTEN, BRCA2, BRCA1, RB1 and TP5330." (PMID 36805510, 2023). "On the other hand, some cancers previously taken into consideration for screening for BRCA1/2 carriers, like melanoma, may be reconsidered, to further optimize cancer prevention screening strategies and eventually reduce carriers' distress." (PMID 35077220, 2022). "However, a high level of protein expression fragment of BRCA1 in the melanoma cell is indicated as being pro-apoptotic and continues or enhances the apoptotic program." (PMID 34199079, 2021). "We have confirmed the regulation of four exemplary genes, namely RAD51, BRCA1, BRCA2, and XRCC2 by vemurafenib treatment in further BRAF-mutated melanoma cell lines using RT-qPCR analysis at the mRNA level and the regulation of Rad51 at protein level using immunoblot analysis." (PMID 32719412, 2020). "It should be noted that large‐scale studies of this type cannot conclude that BRCA1 or BRCA2 variants never contribute to melanoma formation, just that at a population level they are not major contributors to the burden of disease." (PMID 31610093, 2020). "We found that several HRR-associated genes, including DDB2, RAD51, BRCA1, XRCC2 and BRCA2, are overexpressed in melanoma cells compared to primary melanocyte cultures, while the expression of the NER-associated genes XPA, ERCC1 and ERCC4 showed no clear differences." (PMID 32719412, 2020). "Given this function of BRCA1, it is likely that the upregulation of BRCA1 gene expression could be a compensatory mechanism in response to melanoma progression." (PMID 32079144, 2020). "Overall, 61 of 218 (28.0%) BRCA1/2 variant-positive individuals had a documented personal history and 98 (45.0%) had either a personal or family history of HBOC-related cancer (breast, ovarian, pancreatic, prostate, or melanoma)." (PMID 31892343, 2019). "The lack of BRCA1 mutations in our melanoma patients supports the notion that it is not involved in MM development." (PMID 30286154, 2018). "For example, it was reported that melanoma patients with germline variants in MC1R tended to acquire BRCA1 mutations more likely than those without genetic variants in MC1R." (PMID 27821817, 2017). "Regarding skin cancer or melanoma, it has not been clearly defined whether these neoplasms are manifestations of the BRCA1/2 mutation carrier status." (PMID 40649916, 2025). "The association of BRCA1/2 mutations with melanoma is not completely determined; the interpretation of variants of unknown significance is also problematic." (PMID 30286154, 2018). "BRCA1 mutations have not been significantly associated with melanoma." (PMID 27776349, 2017).
melanoma (continued). "A highly significant overlap of transcript expression in melanoma cell lines after cisplatin treatment with transcripts involved in DNA repair and DNA damage response genes BRCA1, BRCA2, ATM and CHEK2 was observed, which may be compensating for diminished NER capacity." (PMID 23940574, 2013). "Thus, the advent of PARP inhibitors in the field of melanoma treatment has brought much excitement and potential to the field of targeted cancer therapy, particularly for patients with clinically significant genetic alterations, such as HRD and BRCA1/2 mutations." (PMID 40842586, 2025). "The protein–protein interaction (PPI) network analysis identified hub genes such as MYC, BRCA1 and AURKB, which play critical roles in melanoma biology." (PMID 39823244, 2025). "This higher CtBP1/BARS protein level commits cell proliferation and genome instability endorsing melanoma initiation and progression by CtBP1/BARS-mediated transcriptional repression of CDKN2A gene and Brca1 gene." (PMID 38711119, 2024). "We have shown an overexpression of RAD51 and other HRR genes, DDB2, XRCC2, BRCA1 and BRCA2, in melanoma cell lines and this has a protective role against DNA damage accumulation after genotoxic stress." (PMID 32719412, 2020). "Given that we have identified limited induction of BRCA1 in the melanoma cell lines in response to cisplatin in this study, the result was not unexpected and may be indicative of other BRCA1-associated DNA repair transcripts undergoing normal response to DNA-damage inducing stimuli." (PMID 23940574, 2013). "While the efficacy of PARP inhibitors was first demonstrated against solid tumors with BRCA1/2 mutations and HRR defects, these alterations are not universally present in melanoma patients given the molecular heterogeneity of melanoma." (PMID 40842586, 2025). "Early studies of women who carry BRCA mutations found an increased risk of melanoma in family members of BRCA2 carriers However, this was not seen in a recent study of BRCA1 and BRCA2 families described by the CIMBA consortium." (PMID 38741145, 2024). "Therefore, we analyzed gene expression of the important HRR genes BRCA1, BRCA2, RAD51, and EXO1 after MAPKi treatment in MAPKi S, R, and RR A375 melanoma cells." (PMID 37674529, 2023). "Specifically, we applied a mRNA panel consisting of KI67 (indicative of cell proliferation), POLR2A, BRCA1, MTOR, NCOA2, and NCOA3 to highly scattering and autofluorescent human melanoma skin biopsy FFPE tissues obtained from and characterized by the UCI Dermatopathology Center." (PMID 35013281, 2022). "Non-metabolism-related proteins (BRCA1, phosphorylase B kinase regulatory subunit: PHKA1, tyrosine-protein kinase receptor: ALK and rho-associated protein kinase: ROCK1) correlated to melanoma development differed among all groups." (PMID 34199079, 2021). "Of the two, BRCA2 has traditionally been described with a stronger, albeit still relatively weak, link to melanoma development, though recent data indicates neither BRCA1 nor BRCA2 are likely to have a significant impact on the melanoma risk." (PMID 34638397, 2021). "A previous PPI network analyses conducted in a whole gene expression dataset of 31 primary melanomas and 52 metastases reported a PPI network in which PCNA, CDK1, MAD2L1, RFC4 and BRCA1 genes showed highest degree centrality values among upregulated genes in metastases." (PMID 28030792, 2017).
melanoma (continued). "Although this finding is irrespective of treatment, it is tantalising and requires further investigation given recent reports of BRCA1 being overexpressed in melanoma non-responders to chemotherapy and patients with melanoma relapse." (PMID 23940574, 2013). "Whether the increased expression of BRCA1 and CHEK1 may account for the increased expression of cell cycle genes and decreased expression of apoptotic target genes in melanoma is yet to be determined." (PMID 21615965, 2011). "No germline BRCA1/2 VUS/CIP was detected in melanoma patients." (PMID 38974244, 2024). "Regarding melanoma, while risk estimates were not reliable for most genes due to a smaller melanoma cohort size, PVs in CDKN2A were expectedly associated with very high risks for melanoma (OR = 114.6); however, PVs in ATM and BRCA1 were also elevated (two- to threefold increased risks)." (PMID 31406321, 2020). "This raises the possibility that the BAP1-BRCA1 interface is important for tumor suppression though melanoma is not usually considered a canonical tumor within the BRCA1 cancer spectrum and BRCA1 has not been shown to be significantly mutated in either CM or OM." (PMID 22545102, 2012). "Therefore, the association between melanoma and non-melanoma skin cancers in patients with BRCA mutations remains an active area of investigation, and there are no official recommendations on to perform skin screening in BRCA1/2 mutation carriers." (PMID 35573021, 2022). "PCNA, BRCA1 and XPB displayed a lack of induction and highly correlated with altered expression in melanoma after cisplatin treatment by GSEA, therefore they were further investigated in 157 primary and metastatic melanoma tumours." (PMID 23940574, 2013). "The GGR regulators, BRCA1 and PCNA, were induced in melanocytes after cisplatin, but not in melanoma cell lines." (PMID 23940574, 2013). "In this study we have confirmed that the GGR regulators, BRCA1 and PCNA, are induced in the normal cellular response to cisplatin induced DNA damage, but there is complete absence of induction of these regulators in melanoma cell lines." (PMID 23940574, 2013). "Importantly, DNA repair transcripts PCNA and BRCA1, both of which have previously been reported to regulate DDB1 and DDB2 transcript expression, had significantly higher induction in melanocytes 24 hours after cisplatin treatment but not in the majority of the melanoma cell lines." (PMID 23940574, 2013).